LMOD1 (leiomodin 1)
Description:
Required for proper contractility of visceral smooth muscle cells. Mediates nucleation of actin filaments.
Synonyms: SM-Lmod; 64kD; D1; 1D; SMLMOD; MMIHS3
Tractability: Small molecule: a structure with a bound ligand is known.
Gene: Protein-coding gene on chromosome 1 (201,896,456 to 201,946,551, reverse strand). Ensembl gene ENSG00000163431.
Subcellular location: Cytoplasm, myofibril, sarcomere; Cytoplasm, cytoskeleton
Subcellular location (Human Protein Atlas): Cytosol
Pathways (Reactome):
Muscle contraction: Smooth Muscle Contraction
Gene Ontology:
Molecular function: actin binding; tropomyosin binding
Biological process: actin nucleation; positive regulation of actin filament polymerization; actin filament organization; muscle contraction; myofibril assembly; pointed-end actin filament capping
Cellular component: myofibril; actin filament; cytoskeleton; cytosol; membrane; sarcomere; striated muscle thin filament
Genetic constraint (gnomAD): Loss-of-function variants: 8 observed, 38.07 expected, observed/expected ratio (o/e) 0.21, 90% interval 0.12 to 0.38. The upper end of that interval is the gene's LOEUF score, 0.38, which puts it in group 1 of 6, group 1 being the genes least tolerant of losing a copy. Missense variants: 630 observed, 784.94 expected, observed/expected ratio (o/e) 0.8, 90% interval 0.75 to 0.86. Synonymous variants: 281 observed, 301.41 expected, observed/expected ratio (o/e) 0.93, 90% interval 0.85 to 1.03.
Homologues: Orthologues: chimpanzee LMOD1 (99% identical), macaque LMOD1 (97% identical), guinea pig LMOD1 (86% identical), mouse Lmod1 (83% identical), rabbit LMOD1 (82% identical), rat Lmod1 (82% identical), pig LMOD1 (79% identical), dog LMOD1 (78% identical), tropical clawed frog lmod1 (50% identical), zebrafish lmod1b (43% identical), zebrafish lmod1a (40% identical), Drosophila melanogaster tmod (19% identical), and 1 more. Paralogues in human: LMOD2 (36% identical), LMOD3 (31% identical), TMOD2 (22% identical), TMOD3 (22% identical), TMOD1 (22% identical), TMOD4 (19% identical).
Diseases named in the same sentence as LMOD1 in open-access papers:
LMOD1 is named in the same sentence as 59 diseases in open-access papers, as found by Europe PMC text mining. Sharing a sentence is not in itself a finding about the gene and the disease. The quoted sentences say what the papers report.
coronary artery disease (7 papers, 2018 to 2025). "The LMOD1 gene has been identified as a risk locus in coronary artery disease,its expression has been found to be reduced in SMCs within atherosclerotic lesions, and its reduced expression is associated with decreased cell contraction." (PMID 37891618, 2023). "In a previous study, LMOD1 was identified as one of 15 new potential risk loci in the pathogenesis of coronary artery disease." (PMID 36292702, 2022). "LMOD1 gene has been identified as a causal gene for coronary artery disease by maintaining the differentiated SMC phenotype." (PMID 36552740, 2022). "LMOD1, another target gene of MYOCD/SRF that falls with increasing age, was uncovered in genome wide association studies for coronary artery disease, raising the possibility LMOD1 depletion may play a role for the age-dependence of atherosclerosis." (PMID 40081573, 2025). "LMOD1, identified by our TWAS, is a coronary artery disease associated locus believed to regulate contractility in visceral smooth muscle cells." (PMID 36056064, 2022). "Interestingly, we found that LMOD1 is a target gene for coronary artery disease from GWAS catalog." (PMID 36552740, 2022).
atherosclerosis (4 papers, 2018 to 2025). A disease characterized by the build-up of fatty material and calcium deposition in the arterial wall resulting in partial or complete occlusion of the arterial lumen. "Future studies using single-cell transcriptomic profiling in lineage-traced SMCs during atherosclerosis may further define the causal functional role of LMOD1 as a key regulator of SMC transformation during the disease process." (PMID 30444878, 2018). "While LMOD1 appears to selectively mark differentiated SMCs in vivo, the functional effects of LMOD1 deficiency should also be validated in vivo using various models of atherosclerosis progression." (PMID 30444878, 2018). "More importantly, we show that reduced Leiomodin 1 results in phenotypic modulation of smooth muscle cells, a process related to diseases such as atherosclerosis." (PMID 30444878, 2018). "Thus, we queried the relative expression of all genes at the LMOD1 locus in atherosclerosis prone tissues such as human coronary artery in the GTEx dataset." (PMID 30444878, 2018). "Given the direction of the human genetic association studies and prior expression analyses in carotid arteries, these results suggest that LMOD1 may serve a protective role in the setting of atherosclerosis, and potentially stabilize the developing lesion." (PMID 30444878, 2018). "Using this dataset we identified a strong correlation of LMOD1 and FOXO3 transcripts, which suggests that LMOD1 and FOXO3 may be co-regulated during atherosclerosis in vivo." (PMID 30444878, 2018).
epilepsy (3 papers, 2020 to 2022). A brain disorder characterized by episodes of abnormally increased neuronal discharge resulting in transient episodes of sensory or motor neurological dysfunction, or psychic dysfunction. "Here, we screened serum and CSF samples of persons with nodding syndrome and other forms of onchocerciasis-associated epilepsy (OAE) and African and European controls for leiomodin-1 antibodies by a cell-based assay (CBA) and Western blot (WB)." (PMID 34357995, 2021). "Future longitudinal studies investigating the development of leiomodin-1 antibodies and the development of neurologic diseases including epilepsy could inform this hypothesis." (PMID 33321732, 2020). "Collectively, these data suggest that leiomodin-1 antibodies are directly interacting with membranous leiomodin-1 in newly formed neurons to initiate a neurotoxic cascade and may thus be contributing to the development of epilepsy." (PMID 33321732, 2020). "Leiomodin-1 antibodies were detected in the serum of 6/52 (12%) persons with OAE compared to 14/61 (23%) controls without epilepsy (p = 0.113) by a cell-based assay." (PMID 34357995, 2021). "Leiomodin-1 antibodies were detected by CBA in 6/52 (12%) and by WB in 23/54 (43%) persons with OAE compared to in 14/61 (23%) (p = 0.113) and 23/54 (43%) (p = 0.479) of controls without epilepsy." (PMID 34357995, 2021).
gastric cancer (3 papers, 2022 to 2023). A primary or metastatic malignant neoplasm involving the stomach. "In the current study, we used the WGCNA algorithm to find gene enrichment modules associated with diffuse and intestinal gastric cancer and selected the hub gene, LMOD1, to determine the molecular mechanism of Lauren classification." (PMID 35488236, 2022). "LMOD1 was found to be a new gastric cancer biomarker and therapeutic target that induces EMT by regulating the FAK-Akt/mTOR pathway." (PMID 38144520, 2023). "As an oncogene related to Lauren classification, LMOD1 modulates gastric cancer cell metastasis via the FAK-AKT/mTOR pathway." (PMID 37963970, 2023). "According to the LMOD1 immunohistochemical scores, 102 patients with gastric cancer were divided into a low-expression group (38/102) or a high-expression group (64/102)." (PMID 35488236, 2022). "To explore the role of LMOD1 in the occurrence and development of gastric cancer, we used TCGA and GSE62254 databases to analyze LMOD1 with GSEA." (PMID 35488236, 2022). "LMOD1 promoted the migration of gastric cancer cells by regulating the FAK-Akt/mTOR pathway in vitro." (PMID 35488236, 2022). "The expression of LMOD1 in GES-1 cells was lower than that in gastric cancer cell lines, further supporting that LMOD1 is a cancer-promoting gene." (PMID 35488236, 2022). "LMOD1 can therefore promote peritoneal metastasis of gastric cancer cells and can be used as a novel therapeutic target for gastric cancer." (PMID 35488236, 2022). "To explore the expression and prognostic significance of LMOD1 in clinical tissues of patients with gastric cancer, we measured the protein expression of LMOD1 in 48 pairs of gastric cancer and adjacent tissue samples." (PMID 35488236, 2022). "Next, we examined the expression of LMOD1 in 102 gastric cancer tissues and 40 paracancerous tissues using immunohistochemistry, which also showed that the expression of LMOD1 in gastric cancer tissues was higher than that in paracancerous tissues." (PMID 35488236, 2022). "By analyzing the relationship between LMOD1 expression and Lauren classification in GEO databases, we found that patients with high LMOD1 expression had diffuse gastric cancer, while patients with low LMOD1 expression were more likely to have intestinal gastric cancer." (PMID 35488236, 2022). "In vitro and in vivo experiments verified that LMOD1 could affect the migration ability of gastric cancer cells by regulating the FAK-Akt/mTOR pathway, which can alter the EMT of cells to promote the occurrence of peritoneal metastasis in gastric cancer." (PMID 35488236, 2022). "In this study, a GSEA analysis and western blotting demonstrated that LMOD1 could alter the migration ability of gastric cancer cells by regulating FAK-Akt / mTOR pathway." (PMID 35488236, 2022). "To answer whether LMOD1 could promote peritoneal metastasis of gastric cancer by affecting EMT, we predicted that LMOD1 could be enriched in the EMT pathway in the TCGA and GSE62254 databases." (PMID 35488236, 2022). "In vivo and in vitro experiments further confirmed that LMOD1 could promote peritoneal metastasis by regulating EMT of gastric cancer cells." (PMID 35488236, 2022). "In this study, we constructed a WGCNA analysis model by combing the information on gastric cancer patients from Gene Expression Omnibus (GEO) databases, and selected LMOD1 as our research gene target for the modules highly related to the Lauren classification data." (PMID 35488236, 2022). "Our results suggest that LMOD1 can upregulate the expression of FAK, activate the phosphorylation level of the Akt / mTOR pathway, promote EMT in gastric cancer cells, increase cell invasion and migration, and promote the occurrence and development of peritoneal metastasis of gastric cancer." (PMID 35488236, 2022). "Since, LMOD1 had not been previously studied in relation to gastric cancer, this gene was chosen for further study." (PMID 35488236, 2022).
gastric cancer (continued). "LMOD1 was found to regulate the FAK-Akt/mTOR pathway to induce EMT of gastric cancer cells, to further increase invasion and adhesion of gastric cancer cells and promote peritoneal metastasis of gastric cancer cells." (PMID 35488236, 2022). "Additionally, a Gene Set Enrichment Analysis using the TCGA and GSE62254 databases, and western blot data, showed that LMOD1 could promote an epithelial-mesenchymal transition (EMT), thus potentially affecting the occurrence of peritoneal metastasis of gastric cancer." (PMID 35488236, 2022).
autoimmune disease (2 papers, 2021). A disorder resulting from loss of function or tissue destruction of an organ or multiple organs, arising from humoral or cellular immune responses of the individual to their own tissue constituents. "There are also several arguments against the hypothesis that nodding syndrome is an autoimmune disease caused by leiomodin-1 antibodies." (PMID 34357995, 2021). "In conclusion, our data do not support OAE to be an autoimmune disorder caused by leiomodin-1 antibodies." (PMID 34357995, 2021).
Autoimmunity (2 papers, 2016 to 2020). The occurrence of an immune reaction against the organism's own cells or tissues. "A recent study suggests that an antibody-mediated autoimmune response to leiomodin-1 is involved in the etiology of NS, and that autoimmunity due to molecular mimicry of an O. volvulus surface protein contributes to NS pathogenesis." (PMID 27005304, 2016). "However, as leiomodin-1 expression and epitope availability in human neurons remains uncharacterized, the relevance of leiomodin-1 autoimmunity is unknown." (PMID 33321732, 2020).
carotid atherosclerosis (2 papers, 2018 to 2025). A thickening and loss of elasticity of the walls of carotid arteries that occur with formation of atherosclerotic plaques. "While previous reports demonstrated differential staining of LMOD1 in carotid atherosclerosis, it was still not clear what type of SMCs are implicated." (PMID 30444878, 2018).
heart failure (2 papers, 2014 to 2023). Inability of the heart to pump blood at an adequate rate to meet tissue metabolic requirements. "The presence of leiomodin-1 in the smooth muscle and the cytoskeleton links well to a pathological role in heart failure." (PMID 25117565, 2014). "Some of these proteins, such as lyric and leiomodin 1, were differentially phosphorylated in the two types of heart failure." (PMID 25117565, 2014). "Generation of mutants in leiomodin-1 unable to be phosphorylated at the amino acids revealed herein will be critical in determining the involvement of this relatively uncharacterized protein in the development of these two distinct types of heart failure." (PMID 25117565, 2014).
Megacystis (2 papers, 2024 to 2025). Dilatation of the bladder postnatally. "One male patient in this cohort had a homozygous LMOD1 missense mutation with an overall favorable outcome at the last follow-up and featured megacystis, partial duodenal stenosis, status after temporary PN support currently under enteral nutrition, and cholelithiasis." (PMID 41387873, 2025). "Megacystis-Microcolon-Intestinal Hypoperistalsis Syndrome has five types caused by MYLK, MYH11, LMOD1, MYL9, and ACTG2 genes and has unknown prevalence." (PMID 39480826, 2024).
acute coronary syndrome (1 paper, 2022). Signs and symptoms related to acute ischemia of the myocardium secondary to coronary artery disease. "The aim of this case-control association study was to evaluate the associations between the occurrence of acute coronary syndromes in the form of unstable angina and SNPs within the PECAM1, COL4A2, PHACTR1 and LMOD1 genes." (PMID 35054067, 2022).
arteriosclerosis (1 paper, 2022). A vascular disorder characterized by thickening and hardening of the walls of the arteries. "LMOD1 exhibits potential as a promising diagnostic and therapeutic biomarker for arteriosclerosis." (PMID 36292702, 2022). "Following validation, LMOD1 was identified as the target gene, which was hypermethylated and downregulated in arteriosclerosis." (PMID 36292702, 2022).
Berdon's syndrome (1 paper, 2021). "The mutation of the following genes: MYH11, MYLK, LMOD1, and MYL9, is also involved in the pathogenesis of Berdon's syndrome in individual cases." (PMID 33859849, 2021).
bladder cancer (1 paper, 2023). "Consistent with our study, previous studies have reported these key genes (TAGLN, CNN1, ACTC1, LMOD1) play important roles in bladder cancer." (PMID 38144520, 2023).
brain tumors (1 paper, 2023). "For the other identified candidate biomarkers (EDDM3B, LMOD1, GP2, SPINT3, CTRL, OXT) there is no specific literature linking them to gliomas or other brain tumors." (PMID 36959545, 2023).
cardiac hypertrophy (1 paper, 2014). "Leiomodin-1 is primarily expressed in smooth muscle, with some expression in the heart, and is speculated to play a role in cardiac hypertrophy and muscle contraction." (PMID 25117565, 2014).
cardiomyopathy (1 paper, 2020). A disease of the heart muscle or myocardium proper. "Additionally, as leiomodin-1 is expressed in blood vessels, it has been suggested that if antibodies to leiomodin-1 were pathogenic it would result in myopathy or cardiomyopathy." (PMID 33321732, 2020).
Cerebellar atrophy (1 paper, 2020). Cerebellar atrophy is defined as a cerebellum with initially normal structures, in a posterior fossa with normal size, which displays enlarged fissures (interfolial spaces) in comparison to the foliae secondary to loss of tissue. "This correlative observation suggests that immune responses to leiomodin-1 could target these regions, resulting in pathology such as cerebellar atrophy as well as abnormal growth and development." (PMID 33321732, 2020).
endothelial dysfunction (1 paper, 2018). In vascular diseases, endothelial dysfunction is a systemic pathological state of the endothelium (the inner lining of blood vessels) and can be broadly defined as an imbalance between vasodilating and vasoconstricting substances produced by (or acting on) the endothelium. "SERPINH1 (rs590121 lead SNP) is predicted to increase risk of hemorrhage; DDX59-CAMSAP2 (rs1867624) may be involved abnormal vascular development; PECAM1 (rs1867624) may regulate vascular inflammation and endothelial dysfunction; and LMOD1 (rs2820315) is implicated in SMC differentiation." (PMID 30444878, 2018).
glioblastoma (1 paper, 2020). The most malignant astrocytic tumor (WHO grade IV). "To further confirm leiomodin-1 expression in neurons and glia, we performed qPCR from neurons and astrocytes differentiated in vitro as well as representative cancer cell lines of the CNS including glioblastomas (U251, SF295) and neuroblastoma (SH-SY5Y)." (PMID 33321732, 2020).
Hashimoto thyroiditis (1 paper, 2022). An autoimmune disorder caused by the production of autoantibodies against thyroid tissue. "Leiomodin 1 (LMOD1) was initially identified as 64 kDa autoantigen in a serum expression screen in Hashimoto’s thyroiditis." (PMID 35488236, 2022).
idiopathic pulmonary fibrosis (1 paper, 2021). Idiopathic pulmonary fibrosis (IPF) is a nonneoplastic pulmonary disease that is characterized by the formation of scar tissue within the lungs in the absence of any known cause. "Among all upregulated DEGs of AT1, LMOD1 (logFC = 1.09), a reported marker gene for idiopathic pulmonary fibrosis, ranked here as the most upregulated gene." (PMID 32913304, 2021).
malaria (1 paper, 2021). Malaria is a serious and sometimes fatal disease caused by a parasite that commonly infects a certain type of mosquito which feeds on humans. "We cannot exclude that leiomodin-1 antibodies might cross-react with other common parasites co-endemic with O. volvulus but absent in American and European populations, such as other filarial parasites or malaria." (PMID 34357995, 2021).
melanoma (1 paper, 2026). A malignant, usually aggressive tumor composed of atypical, neoplastic melanocytes. "Overexpression of LMOD1 has been shown to increase apoptosis and CD4+ T cells and activate oxidative stress in melanoma." (PMID 41596347, 2026).
metabolic syndrome (1 paper, 2025). A cluster of metabolic risk factors for CARDIOVASCULAR DISEASES and TYPE 2 DIABETES MELLITUS. "Of note, in a murine model of combined metabolic syndrome (MetS) and atherosclerosis (KKAy+/−ApoE−/−), we recently reported that upregulated TSP1 expression directly associates with increased atherosclerotic lesion burden, accompanied by attenuated LMOD1 and SRF expression in the aortic vasculature." (PMID 40940776, 2025).
neuroblastoma (1 paper, 2020). Neuroblastoma (NB) is the most common solid, extracranial childhood tumor. "LMOD1 transcripts were significantly enriched in the neuroblastoma cell line SH-SY5Y (mean ± SD = 7701 ± 932.5, p = 0.0007, Kruskal–Wallis test) and in astrocytes (mean ± SD = 1003 ± 682.1, p = 0.01, Kruskal–Wallis test) as compared to liver (mean ± SD = 30.12 ± 32.45)." (PMID 33321732, 2020).
pulmonary hypertension (1 paper, 2016). Increased pressure within the pulmonary circulation due to lung or heart disorder. "Using Ingenuity Pathway Analysis (IPA), we discovered a strong association among pulmonary hypertension, MEF2C, LMOD1, and miR-214." (PMID 27144530, 2016).